BRCA1 (BRCA1 DNA repair associated)
Diseases named in the same sentence as BRCA1 in open-access papers (continued):
Sharing a sentence is not in itself a finding about the gene and the disease.
cancer (continued). "Thus, expression of other transporters, or different drug resistance mechanisms, such as aldehyde dehydrogenase, which was over-expressed in both CD44+/CD24- and CD133+ cell types, may be operational in Brca1 cancer stem cells." (PMID 18241344, 2008). "No studies have yet been conducted to characterize Brca1-deficient cancer stem cells." (PMID 18241344, 2008). "Thus, investigating the BRCA1 pathway could be an important approach for the treatment of basal-like cancer." (PMID 19007432, 2008). "However, the BRCA1 protein is known to act in DNA repair, and other pleiotropic effects beyond preventing cancer onset are to date unknown." (PMID 18030340, 2007). "The two MBC cases without family history of cancer resulted negative for BRCA1/2 mutations." (PMID 16764716, 2006). "The frequency of ER-positive cancers among our control cancers is quite high, which might be due to a later year of diagnosis than for non-BRCA1/2 cancers and in general because of age distribution, mammography screening or ethnic differences in different populations." (PMID 15642173, 2005). "Accordingly, the lack of a need for X chromosome inactivation and X-linked gene dose adjustment in men may explain why male BRCA1 mutation carriers do not have the same increased risk for cancers." (PMID 15383145, 2004). "We further extended this framework to five additional cancer-related genes (VHL, ATM, BRCA1, RAD51C, and BAP1), establishing a generalizable framework for gene-specific VEP with potential applications in precision medicine." (PMID 41955512, 2026). "A considerable proportion of clonal 6p LOH is observed in patients with BRCA1/2 alterations, and the functional consequence of 6P LOH in HRD cancers, namely, an increase in dysfunctional CD4+ and CD8+ T cells, is also demonstrated." (PMID 40830526, 2025). "An increasing number of studies have highlighted that key cancer-associated neoantigens and spliceosomal proteins are frequently altered in cancer, leading to pathogenesis and/or treatment resistance, such as in the HER2 and BRCA1 isoforms." (PMID 41194925, 2025). "Of individuals with cancer known/found to carry germline P/LPV, between 53% and 61% were offered germline genotype‐directed therapies, many of whom were BRCA1/2 positive." (PMID 40747594, 2025). "Among cancer cases performed using MLPA, six cases of BRCA1 showed CNV values matching ddPCR results (CNVs = 1.6 ± 0.1), while eight cases of BRCA2 detection matched with ddPCR results (CNVs = 1.9 ± 0.1)." (PMID 40725150, 2025). "Beyond BC, BRCA1 and BRCA2 also play roles in other types of cancer, such as melanoma, pancreatic, prostate, biliary tract, esophageal cancer, and gastric cancer." (PMID 40071159, 2025). "Due to limited sample sizes for single gene alterations, similar phenomena were also observed for BRCA1 and BRCA2 in some cancers." (PMID 40420266, 2025). "Using multiple in vitro and in vivo systems, we show that BRCA1/2 and ADAR1 are synthetically lethal, and that ADAR1 activity is upregulated in BRCA1/2-mutant cancers." (PMID 40730818, 2025). "The incidence rate of BRCA1 vs. BRCA2 PCa and other cancers was investigated through the Consortium of Investigators of Modifiers of BRCA1/2 (CIMBA), comprising data from 6902 men worldwide (33 countries)." (PMID 40002276, 2025). "In particular, breast cancer gene 1 (BRCA1) and breast cancer gene 2 (BRCA2), which are critical in human cancer, also influence the development and progression of canine tumors." (PMID 40004231, 2025).
cancer (continued). "Together, BRCA1 and BRCA2 cooperate in a concerted effort to repair damaged DNA, regulate cell growth, and prevent cancer development by ensuring that the cell’s genetic material remains stable and intact." (PMID 40004231, 2025). "QD-based diagnostic systems have successfully targeted a broad range of cancer biomarkers, including PSA, carcinoembryonic antigen (CEA), BRCA-1 gene sequences, Fe3+ ions in tumor environments, and even whole cancer cells." (PMID 40801702, 2025). "Somatic inactivation of tumor suppressor genes, such as BRCA1 and MLH1, through promoter methylation leads to gene silencing and contributes to cancer development." (PMID 40495194, 2025). "Both BRCA1 and BRCA2 play pivotal roles in the repair of double‐strand breaks (DSBs) in DNA, which is crucial for preventing genomic instability and cancer development." (PMID 40523654, 2025). "The silencing of BRCA1, MLH1,and MGMT diminishes DNA repair efficiency, resulting in genomic instabilityand contributing to the aging process and cancer." (PMID 39996888, 2025). "DNA polymerase θ (Polθ) is a polymerase-helicasefusionprotein that is synthetically lethal with homologous recombination(HR) factors, such as BRCA1/2, and confers resistance to PARP inhibitors(PARPi) and other genotoxic cancer therapies." (PMID 41124685, 2025). "Therefore, the study could not definitely conclude that BRCA1 methylation reliably predicts the response to PARP inhibitors similar to that of gBRCA mutated cancers." (PMID 39392573, 2025). "Similar findings have been reported for other DNA repair genes, such as BRCA1 and BRCA2, which show tissue-specific effects in cancer prognosis." (PMID 40493574, 2025). "Overexpression of DNA repair proteins, such as BRCA1, PARP1, and RECQL4, enables cancer cells to repair DNA damage induced by chemotherapy, diminishing the effect of treatments like platinum-based drugs and PARP inhibitors." (PMID 40573290, 2025). "We acknowledged the low number of BRCA2 mutation carriers in our collection as well as the differences between BRCA1- and BRCA2-driven cancers, and intentionally limited the study to the BRCA1 gene." (PMID 41374957, 2025). "Detailing the comparative analysis of the BRCA1 and BRCA2 genes in humans and dogs indicates these genes’ critical roles in maintaining genomic integrity and preventing cancer in species." (PMID 40004231, 2025). "The genes BRCA1 and BRCA2 were targeted for knockout (KO) in lymphnode cancer of the prostate (cell line) [LNCaP] using clustered regularly interspaced short palindromic repeats (CRISPR)-Cas9 technology." (PMID 41236806, 2025). "ATRis prevent cellular recovery from PARPi-induced DNA damage and cause rapid cell death by premature mitotic entry with unrepaired DNA damage in BRCA1/2- and ATM-mutant cancer cells." (PMID 39875375, 2025). "BRCA1 induced the expression of glutathione-S-transferase and other antioxidant genes and GSH synthesis in cancer cell lines." (PMID 40863152, 2025). "It is estimated that <5% of BRCA1 and BRCA2 carriers among women with BC are identified in Asia due to major gaps in the availability of cancer-specialised genetic counselling (GC) and access to funded genetic testing (GT) in this region." (PMID 40626014, 2025). "In TNBC, proteins such as BRCA1 and FEN1 repair DNA damage, enabling cancer cells to evade the effects of chemotherapy." (PMID 41049008, 2025). "For instance, MYC directly regulates expression of key HR components such as RAD51, BRCA1, and BRCA2 in multiple cancer contexts." (PMID 41561634, 2025). "In self-identified White patients, PGV rates in ATM, BRCA1, BRCA2, CHEK2 and Lynch genes were significantly higher compared to two cancer-free male cohorts." (PMID 40832411, 2025). "For cell cycle regulation and cancer, the genes CCND1 and E2F7 (cell cycle regulation) and BRCA2, NF2, BRCA1, and NF1 (cancer) were found to be upregulated relative to humans." (PMID 40149424, 2025).
cancer (continued). "The protein has emerged as a promising therapeutic target due to synthetic lethal interactions with BRCA1, SMARCAL1, and RAD52, and in ALT-positive cancers." (PMID 40447800, 2025). "Given the unique and robust regulation of BRCA1 expression by OFD1, targeting OFD1 offers a promising strategy for extending the use of PARP inhibitor therapy to BRCA1 wide-type cancers." (PMID 40764600, 2025). "Evidence suggests that BRCA1 and BRCA2 are crucial targets for innovative canine cancer therapies, offering promising parallels to human medicine and underlining the importance of a comparative approach." (PMID 40004231, 2025). "In this study, we examined the expression of the tumor suppressor gene BRCA1 and the tumor marker CA15-3 in women diagnosed with BC, focusing on different cancer grades." (PMID 39742378, 2024). "Analysing selected promoter probes of BRCA1 and RAD51C, we identified promoter methylation of BRCA1 (meBRCA1) or RAD51C (meRAD51C) in 15 out of 23 cancer types." (PMID 39055334, 2024). "Although the complexity of cancer is well‐acknowledged, the implementation of precision cancer medicine until now has relied on discrete sets of isolated biomarkers (e.g. HR, HER2 and BRCA1/2 in breast cancer)." (PMID 39109701, 2024). "Altogether, these observations point to different roles for BRCA1 and RAD51C methylation in cancer development, progression and therapeutic potential." (PMID 39055334, 2024). "However, multivariate logistic regression demonstrated that having family members with cancer (OR = 2.36, 95% CI = 1.00–5.54), bilateral cancer (OR = 4.78, 95% CI = 1.61–14.20), HER2-(OR = 8.23, 95% CI = 3.25–20.84), Ki67 ≥ 15% (OR = 3.88, 95% CI = 1.41–10.65) were associated with BRCA1/2 mutation." (PMID 38167124, 2024). "BRCA1 recruits both PERK and IRE1, which suggests that BRCA1, PERK, and IRE1 could form a complex under ER stress; BRCA1 deficiency leads to the accumulation of PERK and IRE1, which constitutively activates UPR and promotes survival of BRCA1-deficient cancer cells." (PMID 37470788, 2024). "Our research prompts that BRCA1 expression and the MYC/MYCN-RAD51 axis are pivotal determinants in the anti-cancer efficacy of BI-2536 and further proposes a novel combination therapeutic strategy for SCLC care." (PMID 39085197, 2024). "Therefore, population-based genetic information, in the future, could be useful to improve the detection strategies of BRCA1/2 PV carriers and maximize prevention paths, with significant implications for clinical management and surveillance of male cancer patients and their family members." (PMID 38974244, 2024). "To evaluate the effect of these conditions on cancer cell growth, we conducted CCK8 assays in TYK‐nu cells with stable BRCA1/BRCA2 knockdown." (PMID 39690136, 2024). "PPI of BAP1 with BRCA1 was central to understanding the role of BAP1 in growth-control pathways and cancer; BAP1 was suggested to play a role in BRCA1 stabilisation." (PMID 39516360, 2024). "Simulated uptake of BRRM and RRSO in unaffected BRCA1 and BRCA2 was in line with uptake observed in a familial cancer clinic population and the Lifepool cohort." (PMID 39766065, 2024). "This compromised DNA repair capacity predisposes cells to malignant transformation or apoptosis, highlighting the critical role of BRCA1 and BRCA2 in DNA damage repair in maintaining cellular health and preventing cancer." (PMID 39199310, 2024). "Overall, our findings suggest a possible link between BRCA1 and MGMT epimutations and the occurrence of cancer in the family." (PMID 38542081, 2024). "Our findings indicate that high-level tumour methylation of BRCA1 and RAD51C should be explored as a PARP inhibitor biomarker across multiple cancers." (PMID 39055334, 2024).
cancer (continued). "We subsequently sought to identify the most promising synthetic viability candidates by integrating cancer genomic and transcriptomic analyses with results from recent genome-wide CRISPR knockout screens in BRCA1 and BRCA2 knockout isogenic cell lines." (PMID 39198848, 2024). "BRCA1 and ERα differentially regulate the important proliferation genes C-MYC and CCND1, which are often overexpressed in cancer." (PMID 38892081, 2024). "Additionally, identifying cancer types sensitive to combination treatments and optimizing combination dosages are key to the successful clinical application of combined PARPi and ATRi therapy in BRCA1/2 wild-type cancer patients, necessitating further large-scale studies." (PMID 39156700, 2024). "Despite the higher identification rate of BRCA1/2 PV carriers before the cancer onset related to the implementation of the mass radiogenomic screening, the effect in preventing BRCA-related cancers is limited." (PMID 38195911, 2024). "To further evaluate the likelihood of synthetic viability of our 277 BRCA1 candidates, we turned our attention to DepMap, which has performed genome-wide CRISPR analysis in 1100 cancer cell lines." (PMID 39198848, 2024). "Although most sporadic and hereditary BRCA1 cancers carry the TNBC phenotype (ER−, PR−, HER2−), the majority of hereditary BRCA2 cancers are of a luminal type (HR+, HER2-)." (PMID 38893102, 2024). "As a result, this study aimed to compare BRCA1 gene expression and CA15-3 tumor marker levels across different BC stages, focusing on their correlation with cancer stage and potential utility in prognosis and disease management." (PMID 39742378, 2024). "As a common theme in cancer-related HRD, ssDNA processing and antagonism of BRCA1-53BP1 engagement at DSBs are often perturbed." (PMID 38263342, 2024). "Both BRCA1 expression and CA15-3 levels significantly increased with advanced cancer stages (P < 0.001)." (PMID 39742378, 2024). "Essential proteins frequently overexpressed in cancer cells include PARP, DNA-PKcs, BRCA1/2, ATM, ATR, and Chk1/2." (PMID 39372203, 2024). "In BRCA1mut cancer tissues, BRCA1 expression was significantly higher than in BRCA2mut and BRCA wild-type cancer tissues." (PMID 39080120, 2024). "More recently, Ashworth and colleagues described the synthetic lethal phenomenon as a marked sensitivity of the BRCA1 -/- cell lines to the PARP-1 inhibitors, opening a new era for cancer therapy." (PMID 37409248, 2023). "The genes in Cluster-1, such as MCM2, STAT1, BRCA1, and MCM5, are overexpressed in the cancer samples." (PMID 37925498, 2023). "Despite their close functional connection, BRCA1 and BRCA2 have somewhat different effects on cancer development and progression." (PMID 36902416, 2023). "For a clinical implication, the synergism demonstrated in this study supports the rationale to further investigate the combination of PARP and ATR inhibitors in HRR-deficient cells beyond BRCA1/2 that may give advantages for cancer patients without germline mutations in BRCA1/2." (PMID 36794257, 2023). "However, this might not be the case for hereditary cases, with BRCA2-related cancer as a prominent example where tumours most often are ER-positive but BRCA1/BRCA2-deficient." (PMID 37316882, 2023). "The most common genes in which PPGVs were identified pan-cancer were BRCA2 (16.9% of PPGVs), MUTYH (15.0%), ATM (13.4%), CHEK2 (11.7%), and BRCA1 (9.8%)." (PMID 37568048, 2023). "Indeed, 31.4% of BRCA1/2 PV carriers developed cancer prior to genetic testing, a substantial proportion of which may have been detected earlier through breast surveillance or prevented completely with surgery had these healthy individuals been aware of their high-risk status." (PMID 37887578, 2023).
cancer (continued). "This disputes the risk of false-positive MSP results that may be caused by contamination by cancer cells when analyzing histologically normal adjacent tissues using the MSP technique; hence, any detected methylation in this type of tissue refers to the BRCA1 promoter methylation of normal cells." (PMID 37761820, 2023). "LSD1 inhibition increased the level of transcription-repressive mark H3K9me2 in BRCA1/2 and RAD51 promoter, thus downregulating transcription of these genes and subsequently inducing HR impairment in HR-proficient cancer." (PMID 37973845, 2023). "Our findings expand on prior work where the frequency of non-BRCA1/BRCA2 PVs for women with MPCs (BC and another cancer diagnosis, including a second BC diagnosis) was 8.5% (47/551) among those followed in a high-risk BC program." (PMID 36856935, 2023). "Unexpectedly, the loss of 53BP1 renders BRCA1-deficient cancer cells resistant to PARPi and ionizing radiation (IR) treatment, indicating that loss of 53BP1 expression is at least one determinant for how therapeutic resistance may arise in BRCA-mutated cancers." (PMID 36794849, 2023). "Mechanistically, our lab has shown that in coordination with BLM and FANCM, BRCA1 suppresses the TERRA R-loop accumulation-induced replication stress at the ALT telomeres and is required for the survival of ALT+ cancer cells." (PMID 37035242, 2023). "In 2016, an Australian team published the results of the sequencing of a cancer gene panel comprising ATR for 2000 BC cases with a strong familial history, WT for BRCA1/2 and 1997 healthy controls." (PMID 36749285, 2023). "Among these, the novel frameshift deletion BRCA1 c.2498del was found in two patients diagnosed with unilateral TNBC at young age (31 and 28 years) and with first-degree relatives with cancer." (PMID 37791908, 2023). "Important endocrine system and cancer-related genes and pathways appear to be dysregulated among WTC-exposed individuals; these include WRN, BRCA1, NOTCH1, and NTRK1, among others." (PMID 38131903, 2023). "Further investigation of the revealed founder variants in other cancers in Kazakhs could lead to overlapping results, as these PVs cause truncated or absent BRCA1 and BRCA2 proteins and have already been found in other malignancies where loss of function is a known disease mechanism." (PMID 37791908, 2023). "Prior to categorizing the presence of LGRs across cancer types, to validate the LGR calling method, we used a previously reported copy number sensitive method with ddPCR to detect BRCA1/2 LGRs in 7 samples and RB1 LGRs in eight samples." (PMID 37013911, 2023). "Based on the Cancer Genome Atlas (TCGA) cancer database, we used LASSO regression analysis to identify the six prognostic-related genes with both DDR and EMT functions, including TP63, YWHAZ, BRCA1, CCND2, YWHAG, and HIPK2." (PMID 36673982, 2023). "In fact, two Pol θ inhibitors have been recently reported for the treatment of BRCA1 and BRCA2 related cancers." (PMID 36583344, 2023). "Currently, there are no effective cancer screening methods for OC or prevention strategies to reduce OC risk in the general population, although prophylactic salpingo-oophorectomy has been proven to reduce risk in carriers of pathogenic BRCA1 or BRCA2 variants." (PMID 36833203, 2023). "presented BRCA1 and BRCA2 cancer biology and then introduced the relevant disease modelling systems, thus, providing guidance in drug design." (PMID 37476378, 2023). "The BRCA1 and BRCA2 genes are significant players within the HR pathway, with the impaired function of these genes being the most studied cancer cellular mechanism relating to HRD." (PMID 37808268, 2023). "While these women may never develop cancer, as women without a BRCA1/2 mutation may also develop BC or OC, risk-reducing surgeries such as bilateral mastectomy, bilateral salpingo-oophorectomy, or a combination of both procedures are suggested to reduce the risk of developing BC or OC." (PMID 37445860, 2023).